CD4 (CD4 molecule)
Diseases named in the same sentence as CD4 in open-access papers (continued):
Sharing a sentence is not in itself a finding about the gene and the disease.
Hyperinsulinemia (5 papers, 2017 to 2024). An increased concentration of insulin in the blood. "This analysis revealed that hyperinsulinemia was frequently associated with downregulation of gene transcription in CD4+ cells." (PMID 39768214, 2024). "Insulin suppressed IFNγ production and induced the senescence-associated secretome in CD4+ cell cultures and in patients with hyperinsulinemia." (PMID 39768214, 2024). "In vitro, JAKi treatment synergized with hyperinsulinemia to suppress differentiation of CD4+ cells by inhibiting transcription factors essential for lineage maturation, thereby facilitating senescent effector cell elimination." (PMID 39768214, 2024). "In both cultured CD4+ cells and those isolated from patients with hyperinsulinemia, insulin inhibited IFNγ production by repressing key Th1 transcription factors and cell surface receptors essential for IFNγ signaling." (PMID 39768214, 2024). "Since acute stimulation with insulin inhibited IFNγ production in CD4+ cells, we asked if chronic hyperinsulinemia mirrored this effect." (PMID 39768214, 2024). "Accordingly, hyperinsulinemia maintained its immunosuppressive effect in CD4+ cells of the JAKi-treated patients by mitigating upregulation of the key Th1 transcription factors RORC and PRDM1, as well as the chemokine receptors CXCR3 and CCR5." (PMID 39768214, 2024). "Our analysis of CD4+ T cells from RA patients with hyperinsulinemia revealed that insulin exerts a strong immunosuppressive effect on Th1 cells and regulates cell cycle progression, consistent with findings from in vitro experiments." (PMID 39768214, 2024). "This study aimed to prospectively investigate the impact of insulin signaling and hyperinsulinemia on the function of CD4+ T cells in RA." (PMID 39768214, 2024). "In similarity with CD4+ cells with high GI, the cell cycle genes were deregulated in hyperinsulinemia (GO:0007049, FDR 2.39 × 10−6)." (PMID 39768214, 2024). "In response to hyperinsulinemia, a decrease in the relative content of CD4+ T helper cells and an increase of relative content of CD8+ cytotoxic T cells were detected in both groups of subjects." (PMID 30983877, 2019). "The decrease of the CD4/CD8 ratio of T-lymphocytes evoked by short-term hyperinsulinemia in both groups of subjects suggests a marked role of insulin in the balance of these two cell populations." (PMID 30983877, 2019). "Hyperinsulinemia decreased a relative content of peripheral CD4+ and increased a relative content of CD8+ T lymphocytes, thus decreasing the CD4/CD8 ratio by 18-22% in both groups of subjects." (PMID 30983877, 2019). "We propose here a theoretical simulation study, to explore the molecular interactions between the previously published CD4+ T cell regulatory network and hyperinsulinemia." (PMID 28651594, 2017). "Under high levels of insulin, that simulates an acute hyperinsulinemia condition, the CD4+ T plasticity patterns are altered." (PMID 28651594, 2017). "We model how hyperinsulinemia alters the dynamics of the CD4+ T regulatory network, and this, in turn, modulates cell differentiation and plasticity." (PMID 28651594, 2017). "For now, we used the model to focus on assessing the role of hyperinsulinemia on the differentiation dynamics of an activated CD4+ T cell in VAT." (PMID 28651594, 2017). "Here, we show how hyperinsulinemia shapes CD4+ T cell attainment by reducing the production of IL-10 and causing a shift towards pro-inflammatory, resting, or TGFβ + producing cell types." (PMID 28651594, 2017). "Despite the limitations of the model, the methodological framework proposed here is useful for studying the relationship between CD4+ T cells differentiation and plasticity dynamics and hyperinsulinemia." (PMID 28651594, 2017). "Notably, the dominating majority of DEGs in CD4+ cells of patients with hyperinsulinemia were also DEGs in CD4+ cells with high GI." (PMID 39768214, 2024). "As much as 71% of all DEGs in CD4+ cells of patients with hyperinsulinemia were repressed." (PMID 39768214, 2024).
Hyperinsulinemia (continued). "Moreover, the increased TG was positively associated with the ratio of CD3+CD4+/CD3+CD8+, and was accompanied by reduced insulin sensitivity and hyperinsulinemia." (PMID 33935964, 2021). "In multiple logistic regression analysis, TG was significantly associated with the risk of hyperinsulinemia and increased CD3+CD4+/CD3+CD8+ ratio which was significantly negatively correlated with disposition index (DI30) and DI120, indicators for insulin sensitivity." (PMID 33935964, 2021). "Indeed, the IFNG gene was the top gene repressed in CD4+ cells of patients with hyperinsulinemia." (PMID 39768214, 2024). "To explore the additive effect of insulin and JAKi in RA patients, we compared CD4+ cells within the JAKi-treated (seven with hyperinsulinemia) and non-JAKi-treated groups (five with hyperinsulinemia)." (PMID 39768214, 2024). "Logistic regression analysis for hyperinsulinemia and CD3+CD4+/CD3+CD8+ ratio." (PMID 33935964, 2021). "Hence, we compared the transcriptional profile of CD4+ cells of 12 non-diabetic RA patients with hyperinsulinemia and 44 patients having no hyperinsulinemia." (PMID 39768214, 2024). "Furthermore, an inverse correlation between the CD3+CD4+/CD3+CD8+ ratio and DI values, reflecting insulin sensitivity were found, and increased CD3+CD4+/CD3+CD8+ is an indicator for hyperinsulinemia, revealing the involvement of CD3+CD4+/CD3+CD8+ in RPL patients with IR." (PMID 33935964, 2021).
hyperreactivity (5 papers, 2014 to 2022). "It was suggested that increased CD8+ cytotoxic T lymphocytes and reduction of CD4+ lymphocytes are closely associated with airway hyperreactivity and asthmatic pathologies." (PMID 35656445, 2022).
interstitial nephritis (5 papers, 2013 to 2026). Inflammation of the renal tubules and supporting tissues of the kidney. "Kidney biopsies were performed in five patients, mainly showing interstitial nephritis (3 cases) with or without immune deposition, CD4-positive cell infiltration and interstitial fibrosis." (PMID 36186816, 2022).
juvenile dermatomyositis (5 papers, 2014 to 2024). Juvenile dermatomyositis (JDM) is the early-onset form of dermatomyositis (DM), a systemic, autoimmune inflammatory muscle disorder, characterized by proximal muscle weakness, evocative skin lesion, and systemic manifestations. "Increased CD4+ cells, TH-17, IL-6, an expanded B cell population, and the emerging role of natural killer cells, as well as the PTPN22 R620W variant, are all linked to the increased risk of developing juvenile dermatomyositis." (PMID 34354904, 2021).
lactic acidosis (5 papers, 2011 to 2026). Metabolic acidosis characterized by the accumulation of lactate in the body. "In Bonnet’s case-control study, low creatinine clearance and low nadir CD4+ T lymphocyte count before the inception of NRTI therapy were the main risk factors for lactic acidosis." (PMID 40264671, 2025). "These covariates include; adherence to treatment, development of drug toxicity in the form of peripheral neuropathy and lactic acidosis, change in treatment therapy, gender, age, CD4 baseline and viral load baseline and resistance to treatment on transition intensities are assessed." (PMID 30008270, 2018). "In this study, we explore the effects of treatment toxicity (lactic acidosis (LA) and peripheral neuropathy (PN)), non-adherence (NA), treatment line, CD4 baseline, viral load baseline, age on the changes in the level of viral load in the plasma cells." (PMID 30008270, 2018). "Age, CD4 counts and WHO staging at baseline did not appear to increase the risk of any adverse events after HAART initiation; however, BMIs at baseline did significantly increase the risk of both symptomatic hyperlactataemia and lactic acidosis." (PMID 21923929, 2011).
laryngeal squamous cell carcinoma (5 papers, 2022 to 2025). A squamous cell carcinoma that arises from the larynx. "Studies of laryngeal squamous cell carcinomas have shown that TAN effect decreased CD4+/CD8+ T cell and inhibit production of TNF-α and IFN-γ, resulting in an immunosuppressive environment." (PMID 36765760, 2023). "Infiltration of CD3+, CD4+, and CD8+ T lymphocytes correlates positively with prognosis in laryngeal squamous cell carcinoma (LSCC)." (PMID 40642092, 2025). "A histologic analysis of CD3, CD4, CD8, and CD45RO in TILs in primary laryngeal squamous cell carcinoma was published in a recent study." (PMID 38162490, 2023).
leiomyosarcoma (5 papers, 2013 to 2025). An uncommon, aggressive malignant smooth muscle neoplasm, usually occurring in post-menopausal women. "Conversely, PI3K/mTOR inhibition promotes infiltration and reinvigoration of exhausted PD‐1+CD8+ T cells, sustains a CD4+ Th1 niche, amplifies cytotoxic T cell responses, and sensitizes uterine leiomyosarcomas to PD‐1 blockade." (PMID 41357670, 2025). "High infiltration of CD4+ T cells correlates with better prognosis in dedifferentiated liposarcoma, and elevated densities of CD3+ and CD8+ tumor‐infiltrating T cells—particularly when combined with low NLR—are associated with improved outcomes in pulmonary metastases of uterine leiomyosarcoma." (PMID 41357670, 2025).
leptospirosis (5 papers, 2013 to 2024). A contagious bacterial infection caused by spirochetes of the genus Leptospira. "Previous studies have highlighted the significance of activated CD4+ T cells during Leptospira infection in providing protective immunity to the host and mitigating the severity of leptospirosis by releasing cytokines." (PMID 38496604, 2024). "The levels of TNF-α were higher in CD4+T cells obtained from patients with severe and life-threatening manifestations of leptospirosis than in those from asymptomatic and heathy control subjects." (PMID 33789603, 2021). "However, asymptomatic leptospirosis presented an anti-inflammatory response with higher IL-10-producing CD4+ T-cells compared to patients with severe or mild leptospirosis." (PMID 29974037, 2018). "However, up-regulation of the IL-12b gene of HBMs may not further induce IFN-γ expression in CD4+ T cells during human leptospirosis, since IL-10 in HBMs was also up-regulated and the high-level of IL-10 could suppress the immune response." (PMID 24130911, 2013).
lupus erythematosus (5 papers, 2009 to 2025). An autoimmune, connective tissue chronic inflammatory disorder affecting the skin, joints, kidneys, lungs, heart, and the peripheral blood cells. "Mono may drive pathogenic CD4+ T cell polarization and Ig production, as reported in system lupus erythematosus and chronic Chagas disease." (PMID 34867943, 2021). "These gene sets were predominantly enriched in the B cells, CD4+ T cells, lupus erythematosus B cells, and lupus erythematosus CD4 T cells in the control group." (PMID 37273699, 2023). "and a more recent study showed increased numbers of CD4+CD25−Foxp3+ T-cells in patients with new-onset lupus erythematosus." (PMID 19657390, 2009).
lupus-like syndrome (5 papers, 2009 to 2023). "In their studies with Tregs induced ex-vivo, this group had documented that the combination of CD4 and CD8 Tregs was more effective than CD4 Tregs alone in preventing this lupus-like syndrome." (PMID 34211471, 2021). "In this model, donor CD4+ T cells react to mismatched MHC II on host B cells triggering the polyclonal activation of autoreactive B cells and, eventually, a lupus-like syndrome." (PMID 31057554, 2019).
Middle East respiratory syndrome (5 papers, 2020 to 2023). A viral respiratory infection that is caused by the MERS coronavirus (MERS-CoV), which most often manifests with moderate to severe respiratory symptoms, including productive cough and shortness of breath, which can progress to pneumonia and acute respiratory distress syndrome. "The novel coronavirus is highly comparable to SARS and Middle East Respiratory Syndrome (MERS); both severe respiratory viruses are controlled by CD4 and CD8." (PMID 37465793, 2023). "Survivors of the 2002–2003 SARS outbreak still maintain CD4+ and CD8+ T cell populations reactive to the SARS-CoV-1 nucleocapsid protein, and evidence of sustained T cell memory has also been found for Middle East respiratory syndrome (MERS)." (PMID 32913053, 2020).
monocytopenia (5 papers, 2016 to 2025). "The spectrum of immune cell alterations includes dendritic cells, monocytopenia, loss of transitional B cells, absence of CD56 bright NK cells, reversed CD4:CD8 ratio, excess CD45RA+ CD8+ T cells, and poor humoral response despite normal immunoglobulin levels." (PMID 41322420, 2025). "Monocytopenia was also observed in the G2R398W/+ mice, but the numbers of CD4 single-positive T cells (CD4+ TCs), CD8 single-positive T cells (CD8+ TCs) and granulocytes in mutant mice were comparable to those in control mice and were maintained within the normal range." (PMID 35440757, 2022). "Current smoking, hsCRP, CD4 count and CD8 count were associated with higher odds of having monocytosis but no other variables were associated with either monocytopenia or with monocytosis (respectively)." (PMID 35546661, 2022).
mucositis (5 papers, 2018 to 2024). Mucositis is inflammation and damage of the mucous membranes lining the mouth and other parts of the gastrointestinal (GI) tract. "Decreased proportion of CD3+CD4+CD161+ T cells was associated with the occurrence of mucositis (≥grade 3)." (PMID 29511683, 2018). "However, mucositis was found to be associated with CD4+/CD8+ ratio, which was found to be an immunological risk factor for mucositis." (PMID 34288560, 2021). "Roles of CD4+/IL-17A lymphocytes on intestinal immunity and the pathophysiology of chemotherapy-induced mucositis have been investigated recently." (PMID 33564301, 2021). "Bifidobacterium ameliorated chemotherapy-induced mucositis via promoting the expression of CD4+T cell immunity in rats with cancer." (PMID 33841399, 2021). "Patients with mucositis ≥ grade 3 tended to have a lower proportion of CD3+CD4+CD161+ T cells (4.70 ± 0.65% versus 6.61 ± 0.63%, P = 0.092)." (PMID 29511683, 2018). "The CD4+/CD8+ ratio significantly correlated with mucositis (p = 0.037)." (PMID 34288560, 2021). "However, the CD4+/CD8+ ratio at the time of implant placement was correlated with the presence of mucositis." (PMID 34288560, 2021). "This means that patients' immunological profiles correlated with mucositis, and as the CD4+/CD8+ ratio decreases (specifically when the value falls below 1), the probability of mucositis increases." (PMID 34288560, 2021). "We found that the proportion of circulating CD3+CD4+CD161+ cells is useful for predicting the occurrence of early complications, including mucositis and infections, after ASCT in patients with MM." (PMID 29511683, 2018). "The proportions of CD3+CD4+CD161+ and CD3+CD8+CD161+ T cells were compared according to the occurrence of mucositis (≥grade 3), infection before engraftment, and CMV reactivation." (PMID 29511683, 2018). "However, mucositis significantly correlated with CD4+/CD8+ ratio (p = 0.037); as this ratio decreases, the probability of mucositis increases." (PMID 34288560, 2021). "The multivariate model was adjusted for age, sex, years of HIV infection, years of antiretroviral therapy, number of implants, implant diameter, CD4+ levels at baseline (BL), CD8+ levels at BL, CD4+/CD8+ ratio at BL, platelet count at BL, hemoglobin level at BL, and diagnosis of mucositis." (PMID 34288560, 2021). "However, a correlation was found between the CD4+/CD8+ ratio and mucositis." (PMID 34288560, 2021). "Univariate analysis showed that CD4+/CD8+ ratio was significantly lower in patients with mucositis than that in patients without mucositis (p = 0.037), and as this value decreased, in particular as this value became less than 1, the probability of mucositis increased." (PMID 34288560, 2021).
myeloid malignancies (5 papers, 2014 to 2022). "In patients with advanced-stage myeloid malignancies, treatment with 5-aza led to a significant decrease of IL-4 secreting CD4+ T cells, and a significant increase of IL-17A- and IL-21-secreting CD4+ T cells in the peripheral blood." (PMID 34930302, 2021). "We screened 1,346 patients having undergone HCT for myeloid neoplasms at our center from 1996 to 2016; 443 patients with data on total peripheral blood mononuclear cells (PBMC)/CD4+/CD34+ short tandem repeat (STR) donor chimerism (DC) and follow-up ≥24 months post-HCT were included." (PMID 34950586, 2021).
Neonatal sepsis (5 papers, 2013 to 2024). Systemic inflammatory response to infection in newborn babies. "Integrin α4β1+ Treg (CD3+CD4+CD25+CD127-FOXP3+Integrinα4β1+) frequencies were significantly lower in patients developing neonatal sepsis compared to healthy subjects with prenatal risk factors." (PMID 39072327, 2024). "The primary finding in this study suggests that late-onset neonatal sepsis in VLBW-infants causes an increase in the percentage circulating CD4+ T-cells expressing CEACAM1." (PMID 23894299, 2013). "Late-onset neonatal sepsis in VLBW-infants was associated with an increased percentage CEACAM1 positive CD4+ T-cells." (PMID 23894299, 2013). "While the administration of the miR-146a-3p mimic induced trophoblasts to secrete IL-8, miR-146a-3p transfection lead to a reduction in IL-17 expression in CD4+ T cells from the peripheral blood of children with neonatal sepsis." (PMID 39062931, 2024). "These indicate that GNT exerts its protective effects in neonatal sepsis via activating the STAT5 signaling pathway to mediate the function of CD4+CD25+ Tregs." (PMID 36162982, 2022). "In the VLBW infants with late-onset neonatal sepsis CEACAM1 expression on the CD4+ T-cells correlated with the maximal CRP levels, while in children with meningococcal septic shock serum soluble CEACAM1 concentrations did not correlate with CRP." (PMID 23894299, 2013). "Firstly we tested whether CD4+ T-cell CEACAM1 expression is increased in very low birthweight (VLBW) infants (birth weight 401-1500 gram) with late-onset neonatal sepsis." (PMID 23894299, 2013).
Newcastle disease (5 papers, 2019 to 2025). A condition caused by infection by the Newcastle disease virus, which may be characterized by conjunctivitis, respiratory illness, and diarrhea. "Given its immunomodulatory characteristics, Cs has been used as an adjuvant in vaccines against Newcastle disease, parvovirus, and salmonella, promoting IFNγ production and the proliferation of CD4 as well as CD8 T lymphocytes." (PMID 40733140, 2025). "APS, when used as an adjuvant for oral Newcastle disease vaccination, was shown to increase lymphocyte proliferation and elevate the frequency of CD4+ and CD8+ T cells in peripheral blood and mucosal compartments." (PMID 41031192, 2025). "In hatchling chicks, APS co-administration with the Newcastle disease vaccine elevated serum antibody titers, stimulated lymphocyte proliferation, and increased CD8+ and CD4+ T cell frequencies." (PMID 41031192, 2025). "The lymphocytes, CD4+, and CD8+ populations of IPB-D2 chicken with high Newcastle disease (ND) antibody titers were 65.04%, 10.53%, and 5.47%." (PMID 37576755, 2023).